CHRNA10 (cholinergic receptor nicotinic alpha 10 subunit)
Description:
Component of neuronal acetylcholine receptors (nAChRs) that function as pentameric, ligand-gated cation channels with high calcium permeability. nAChRs are excitatory neurotrasnmitter receptors formed by a collection of nAChR subunits. Each nAchR subunit confers differential attributes to channel properties, including activation, deactivation and desensitization kinetics, pH sensitivity, cation permeability, and binding to allosteric modulators (Probable). Forms heteropentamers with CHRNA9. Expressed in the inner ear, in sympathetic neurons and in other non-neuronal cells, such as skin keratinocytes and lymphocytes. nAChR formed by CHRNA9:CHRNA10 is involved in modulation of auditory stimuli. The channel is permeable to a range of divalent cations including calcium, the influx of which may activate a potassium current which hyperpolarizes the cell membrane. In the ear, mediates synaptic transmission between efferent olivocochlear fibers and hair cells of the cochlea, this may lead to a reduction in basilar membrane motion, altering the activity of auditory nerve fibers and reducing the range of dynamic hearing. This may protect against acoustic trauma. May also regulate keratinocyte adhesion (By similarity).
Tractability: Small molecule: a drug acting on it is in phase 2 or 3 trials; a high-quality ligand is known; it belongs to a druggable protein family. Antibody: UniProt places it where antibodies can reach, with medium confidence; UniProt predicts a signal peptide or a membrane-spanning region; its Gene Ontology location is reachable by antibodies, with medium confidence. PROTAC: a small molecule that binds it is known.
Target class: Ion channel; Nicotinic acetylcholine receptor alpha subunit; Ligand-gated ion channel; Nicotinic acetylcholine receptor
Gene: Protein-coding gene on chromosome 11 (3,665,587 to 3,671,384, reverse strand). Ensembl gene ENSG00000129749.
Subcellular location: Synaptic cell membrane; Cell membrane
Pathways (Reactome):
Sensory Perception: Acetylcholine inhibits contraction of outer hair cells
Gene Ontology:
Molecular function: acetylcholine-gated monoatomic cation-selective channel activity; neurotransmitter receptor activity; signaling receptor binding; extracellular ligand-gated monoatomic ion channel activity; monoatomic ion channel activity; transmembrane signaling receptor activity; transmitter-gated monoatomic ion channel activity involved in regulation of postsynaptic membrane potential
Biological process: acetylcholine receptor signaling pathway; positive regulation of cytosolic calcium ion concentration; calcium ion transport; detection of mechanical stimulus involved in sensory perception of sound; monoatomic ion transmembrane transport; regulation of cell population proliferation; regulation of membrane potential; synaptic transmission, cholinergic; chemical synaptic transmission, postsynaptic; excitatory postsynaptic potential; membrane depolarization; monoatomic ion transport; negative regulation of ERK1 and ERK2 cascade; regulation of postsynaptic membrane potential; response to auditory stimulus
Cellular component: acetylcholine-gated channel complex; plasma membrane; membrane; neuron projection; synapse; synaptic membrane; transmembrane transporter complex; axon; cholinergic synapse; perikaryon; postsynaptic membrane; postsynaptic specialization membrane
Genetic constraint (gnomAD): Loss-of-function variants: 30 observed, 31.09 expected, observed/expected ratio (o/e) 0.96, 90% interval 0.72 to 1.31. The upper end of that interval is the gene's LOEUF score, 1.31, which puts it in group 5 of 6, group 1 being the genes least tolerant of losing a copy. Missense variants: 648 observed, 600.72 expected, observed/expected ratio (o/e) 1.08, 90% interval 1.01 to 1.15. Synonymous variants: 302 observed, 268.62 expected, observed/expected ratio (o/e) 1.12, 90% interval 1.02 to 1.24.
Homologues: Orthologues: chimpanzee CHRNA10 (99% identical), macaque CHRNA10 (97% identical), dog CHRNA10 (93% identical), rabbit CHRNA10 (93% identical), guinea pig CHRNA10 (93% identical), pig CHRNA10 (93% identical), mouse Chrna10 (91% identical), rat Chrna10 (90% identical), tropical clawed frog chrna10 (60% identical), zebrafish chrna10a (58% identical). Paralogues in human: CHRNA9 (55% identical), CHRNA7 (40% identical), CHRNA2 (37% identical), CHRNA4 (36% identical), CHRNA3 (34% identical), CHRNA6 (33% identical), CHRNB4 (33% identical), CHRNA5 (33% identical), CHRNB2 (33% identical), CHRNB3 (32% identical), CHRND (32% identical), CHRFAM7A (32% identical), and 33 more.
Diseases named in the same sentence as CHRNA10 in open-access papers:
CHRNA10 is named in the same sentence as 5 diseases in open-access papers, as found by Europe PMC text mining. Sharing a sentence is not in itself a finding about the gene and the disease. The quoted sentences say what the papers report.
hearing loss (3 papers, 2019 to 2025). "Among the 163 upregulated genes, we did not observe a clear enrichment of Gene Ontology processes but did obtain significant enrichment of genes associated with hearing loss, including the upregulation of Otof, Tectb, Cldn11, Sall1, Cldn14, Chrna10, Esprn, and Fgfr3." (PMID 38564333, 2024).
nicotine dependence (1 paper, 2023). Physical and psychological dependence on nicotine. "Chrna10 was identified through linkage analysis in sibling pairs for nicotine withdrawal and was found, together with Chrnd, to increase the risk for nicotine dependence in an African American population subset." (PMID 37295945, 2023).
tumor (1 paper, 2019). "CHRNA5, CHRNA10, CHRNB4, CHRND, CHRNE, and CHRNG, however, were not expressed at levels significantly different from the non-tumor control samples." (PMID 31590360, 2019).
CHRNA10 also shares sentences with these, for which no sentence is quoted: cerebral malaria (1 paper); virus infection (1).